IFNG (interferon gamma)
Diseases named in the same sentence as IFNG in open-access papers (continued):
Sharing a sentence is not in itself a finding about the gene and the disease.
tumor (continued). "Intratumoral delivery of the nanovaccine altered cytokine expression in myeloid cells, reinforced the CXCL9-CD8+ T/IFNγ feedback loop and reversed the immunosuppressive microenvironment, which led to a significantly higher number of infiltrating T cells for tumor eradication." (PMID 35623658, 2022). "Moreover, the ratio of Th1/2 cytokines as well as the levels of IL-12, IL-18, IFNγ and GM-CSF was markedly elevated in RdB/IL-12/IL-18-treated tumours." (PMID 36140243, 2022). "Furthermore, tumor-specific ICOShi+CD4+IFNγ+ T-cells have been identified as a potential biomarker for anti-CTLA-4 response and prognosis in melanoma and bladder cancer patients." (PMID 35326731, 2022). "We next investigated whether KRASG12C inhibitor–driven changes in gene expression affected the capacity of tumor cells to respond to IFNγ." (PMID 35857848, 2022). "Experimental IL-25-signaling blockade (using the D9.2 clone which also blocks human IL-25R) inhibited ILC2 production of IL-4 and IL-13, limiting the suppressive capacities of MDSCs, thereby permitting the liberation of anti-tumor T cell and IFNγ-mediated immunity and reduced CRC." (PMID 35658010, 2022). "Notably, reduced expression of both Ki67 and IFNγ in aPD-1-treated mice compared to the vehicle group was more pronounced in the spleen than in tumour tissue." (PMID 36010935, 2022). "Whereas it is established that defects in the IFNγ receptor complex ablate IFNγ tumor signaling, we hypothesized that, in turn, elevating IFNγ receptor levels may enhance IFNγ signaling." (PMID 35395848, 2022). "The activation of interferon-gamma, inflammatory response, combined with TGF-beta signaling (a signaling pathway linked with immune escape in the tumor microenvironment), may contribute to complicating immune response in this subtype." (PMID 35784457, 2022). "Similarly, human T cells from healthy donors that were pre-activated with IFNγ efficiently induced cell-in-cell formation in allogeneic tumor cells." (PMID 36124553, 2022). "The intersection of the MITF pathway and the interferon-gamma pathway was observed in the tumor intermediate state, which promoted tumor cells to be recognized by CD8+ T cells and might be the cause of the crosstalk propensity." (PMID 35903095, 2022). "However, expression of PD-L1 is likely to be too low to provide an effective target in IFNγ-signaturelow tumours and VISTA would be a more appropriate target." (PMID 36358715, 2022). "Interestingly, both mice treated with either ENI or tumor only SBRT had an increase in CD4 T cells expressing IFNg compared to anti-CD25 only treated mice." (PMID 36385142, 2022). "Additionally, eosinophils are capable of remodelling the TME by expressing natural killer (NK)-cell-associated activation receptors, such as 2B4, NKG2D and LY49, and promoting anti-tumor immunity through release of IFNγ." (PMID 36428768, 2022). "For example, IFNγ+ NK1.1+ Treg cells might lose their pro-inflammatory functions in the immunosuppressive tumor microenvironment." (PMID 36177042, 2022). "In addition, TIGIT also directly induces exhaustion of tumor-infiltrating NK cells with lower expression of IFNγ and TNF or indirectly contributes to exhaustion of CD8+ T cells, impairing anti-tumor immune response." (PMID 36605439, 2022). "As supernatant of activated T cells induced Fas expression on 5T4− tumor cells, we hypothesized that this soluble component present in the supernatant was IFNγ." (PMID 36271507, 2022). "The same results were also obtained with human iPSC-derived iNKT cells, which could be activated by α-GalCer-pulsed DCs and produced as much IFNγ as natural parental cells but exhibited better cytotoxic activity against various tumor cell lines." (PMID 35615083, 2022).
tumor (continued). "Relevant to both OSCC and EBV+-gastric cancer, JAK2/STAT1 signaling has been shown to mediate respectively EGFR- or IRF-1, IFNγ-induced upregulation of the programmed cell death-ligand 1 (PD-L1), an inhibitor of T-cell-mediated tumor cytotoxicity as discussed later in this review." (PMID 35844493, 2022). "We surmised that the much higher basal MHC-I presentation (untreated condition) in these tumour cells may have diminished the IFNγ-dependent increase of MHC-I." (PMID 35982220, 2022). "We and others have shown that IFNγ exposure can up-regulate Fas expression on tumor cells." (PMID 36271507, 2022). "Accordingly, any drug combinations that could reduce the levels of TGF-β, IL-10, and Foxp3 and increase the level of IFNγ, would have a potent inhibitory effect on tumor growth." (PMID 36544523, 2022). "A previous study suggested that higher interferon γ (IFNγ) response was associated with immunotherapy response in GBM, and IFNγ could modulate the immune cell composition in the tumor center." (PMID 35990696, 2022). "Interferon gamma (IFN-γ) is a pleiotropic cytokine with anti-tumor and immunomodulatory function." (PMID 36497451, 2022). "iNKT cells exert anti-tumor effector cell activities by producing several Th1 cytokines, i.e. IFNγ, TNFα, and by eliminating CD1d-expressing tumor cells, thus they represent a potential intriguing therapeutic cellular tool against cancer development and metastasis." (PMID 36338516, 2022). "Next, we asked if inactivation of STUB1 could sensitize human tumour cells to growth inhibition induced by the cytokines such as IFNγ and TNFα." (PMID 35982220, 2022). "T cells positive for either IFNγ or TNFα were defined as tumor reactive." (PMID 35017664, 2022). "We also found that mice pre-treated with CAdTrio showed significantly higher HER2.CART infiltration/expansion (p < 0.005) at the tumor site within 7 days post infusion and increased circulating IFNγ (p = 0.004) in the blood compared to mice treated with HER2.CART alone at 7 days post infusion." (PMID 33742099, 2021). "Further, this combination increased percent of tumor-infiltrating IFNγ+ CD8+ T cells." (PMID 33732652, 2021). "The IFNγ-expressing CAR T cells may change the local tumor microenvironment such as M2-to-M1 macrophage differentiation or stimulate incoming tumor-infiltrating T cells and, thus gradually lead to tumor regression." (PMID 34155235, 2021). "In addition to the direct tumor-killing effects, IFNG, together with IFN-alpha, upregulates the MHC class I molecule expressed on the surface of human GBM cells, increasing the immunogenicity of tumor cells." (PMID 34566988, 2021). "However, obesity induces lipid accumulation driven by PPARα and PPARδ, which causes dysfunction of NK cell metabolism, reduced production of IFNγ, and reduced tumor cell killing." (PMID 34283042, 2021). "CD8+ T cells represent one of the majority of cells that secrete IFNγ in the tumor microenvironment, a process that could promote PD-L1 expression in tumor cells." (PMID 34083572, 2021). "Another study revealed that CD8+ T cells released interferon-gamma (IFNγ) promoted ferroptosis-specific lipid peroxidation in tumor cells via downregulating the expression of SLC3A2 and SLC7A11, and in turn, increased ferroptosis contributes to the anti-tumor efficacy of immunotherapy." (PMID 35071242, 2021). "Studies reported that CD8+ TIL induces PD-L1 expression in tumor cells by producing IFNγ." (PMID 34743724, 2021). "The dual nature of IFNγ in cancer may increase tumor growth by facilitating an immunosuppressive TME." (PMID 35126382, 2021). "In patients with CLL in vivo studies support this finding show that apoptotic tumor cell loaded MoDC produce better T cell proliferation, higher frequency of IFNγ producing T cells via ELISPOT and by PCR less mRNA for the Th2 cytokines IL-4 and IL-10 than cell lysate and mRNA pulsed MoDC." (PMID 33854509, 2021).
tumor (continued). "B cells isolated from TDLNs of 4T1 tumor-bearing mice (a spontaneous metastasis model from 4T1 tumor cells implanted in the mammary fat pad) have been shown to be activated in the presence of irradiated tumor cells and to secrete IgG and IFNg in large amounts after ex vivo coculture." (PMID 34576154, 2021). "Furthermore, PD-L1 expression can be increased in the tumor microenvironment by IFNγ, a cytokine released by activated T cells." (PMID 34290245, 2021). "By combining the detection of intracellular CD137 and de novo production of TNF and IFNγ after recognition of naturally-presented tumor antigens, we demonstrate that a larger fraction of tumor-specific and reactive CD8+ TILs can be detected in vitro compared to commonly used assays." (PMID 34707600, 2021). "Moreover, the observation that tumor-associated macrophages in irradiated tissue have enhanced secretion of pro-inflammatory cytokines IL-6, IL-12, TNF-α, and IFNγ further supports our results." (PMID 34298925, 2021). "miRNAs have regulatory functions: miR-223-3p targets the gene STAT1, involved in interferon-gamma signaling during TB disease; miR-let-7e-5p acts as a tumor suppressor, and its down-regulation may promote the development and progression of carcinomas." (PMID 34804048, 2021). "Despite the controversial roles of cytokines in tumor suppression and immune escape, it is believed that antitumor immunity has mainly relied on IL-12 and IFNγ mediated CD4+ T helper cell activation as well as cytotoxic T lymphocyte (CTL) expansion after pDC presentation." (PMID 35056969, 2021). "Most importantly, we detected baicalein, wogonin and oroxylin A in the Hepa 1–6 tumor and they could potentiate IFNg in the tumor to polarize macrophages into M1-like." (PMID 34188068, 2021). "The main molecular mechanism of this process is mediated by IFNγ, which not only inhibited tumor growth, but also acted on ECs to downregulate the expression of delta-like protein 4, thus inhibiting Notch signaling pathway, which is a key pathway of angiogenesis." (PMID 34476218, 2021). "We have also identified prostasin as a regulator of cytokine and reactive oxygen species production including IFNγ, tumor necrosis factor α (TNF-α) and the inducible nitric oxide synthase (iNOS), all of which are implicated for a role in the tumor microenvironment and progression." (PMID 34240739, 2021). "Overall, these data suggest that under normal (immunocompetent), conditions of tumor growth, there is sufficient immune-dependent IFNγ signaling to drive Ido1 expression, and this can be recapitulated at similar expression levels in vitro by supplementing cultured cells with IFNγ 1 ng/mL." (PMID 33831358, 2021). "IFNG is one of the main anti-tumor cytokines secreted by NK and T cells." (PMID 34868239, 2021). "IL-18, originally termed IFNγ-inducing factor, is considered as a Th1-promoting cytokine since it elicits IFNγ production by T cells, which favors the generation and maintenance of a beneficial inflammatory microenvironment around tumor cells, with potential anti-tumor properties." (PMID 33430344, 2021). "The IFNγ ELISpot performed at 42 weeks after tumor injection in those mice that were still alive strongly suggests that the magnitude of TRP2-specific T cell response correlates with the survival increase (663, 403 and 62 mean SFC/106 cells in IDLV-hTRP2, LV-mTRP2, and IDLV-mTRP2, respectively)." (PMID 33672349, 2021). "Our data pointed to a high density of IFNγ markers and NK cell ligands within the tumor bed relative to other cell types suggesting these immune markers may be very active in early carcinogenesis." (PMID 33987094, 2021). "However, IFNγ produced by CD8+ T cells after radiotherapy can upregulate PD‐L1 expression on tumor cells, which in turn leads to radioresistance." (PMID 34612596, 2021).
tumor (continued). "It has been reported that high levels of IL-10 in tumors inhibit tumor metastasis; tumor cell lines transfected with IL-10 show inhibition of cell growth by increasing IFNγ from CD8+ T cells, and IL-10 transgenic mice stimulate CD8+ T cells and limit the growth of immunogenic tumor cells in vivo." (PMID 33809496, 2021). "Furthermore, splenocytes from vaccinated mice, prior to tumor development, showed enhanced production of the proinflammatory cytokine IFNγ after ex vivo challenge with tumor-cell lines derived from the corresponding model." (PMID 34830945, 2021). "Interferon gamma (IFNg) is a pleiotropic cytokine that can potentially reprogram the tumor microenvironment; however, the antitumor immunomodulatory properties of IFNg still need to be validated due to variable therapeutic outcomes in preclinical and clinical studies." (PMID 34835178, 2021). "Interestingly, this systemic effect was accompanied by an enrichment of tumor-specific IFNγ+CD8+T lymphocytes cells in smLN, the lymphoid structure draining the salivary glands, but not in distal ingLN." (PMID 33917958, 2021). "Interestingly, PD-1+ NK cells were found to have downregulated CD16 expression and induce PD-L1 expression on tumor cells via IFNγ secretion, thus possibly inhibiting ADCC induction." (PMID 34557197, 2021). "Collectively, these findings indicated that ARID5A may be involved in the formation of tumor microenvironment through the interferon-gamma-mediated signaling pathway." (PMID 34094918, 2021). "Similarly, systemic administration of IFNγ to patients with a subset of “cold” sarcomas induced tumor MHC-I expression and T-cell infiltration." (PMID 34201655, 2021). "Consistently with the role of IFNγ signature in driving ICKi response, it has been proposed that upregulation of immunoproteasome subunits in tumor cells might be also involved in this process." (PMID 34638337, 2021). "IFNγ is known to stimulate PD-L1 and increased PD-L1 expression in the more hypoxic tumours could be a direct result of increased IFNy signalling." (PMID 34819027, 2021). "In addition, metformin improves immune response by increasing CD8+ tumor-infiltrating lymphocytes and decreasing inflammatory chemokine production of IL-2, TNFα, and IFNγ." (PMID 34055551, 2021). "Moreover, an increase in the CD69 and IFNγ markers in the splenic NK cell population, a feature similar to that in tumor infiltrating immune populations was observed." (PMID 34696515, 2021). "On the other hand, tumour subclusters with high scores for the differentiated subtype showed an active interferon gamma and interferon alpha response, suggesting, together with high scores in immune cells, an active role of the immune system in differentiated HGSTOC." (PMID 34238352, 2021). "Taking into account the association between IL-18 levels in tumor cells and the density of Th1/Tc1 TILs, our working hypothesis is that this “activated functional inflammasome” of tumor cells can facilitate the IFNγ response of TILs in CRC." (PMID 33430344, 2021). "M2 macrophages secrete pro-tumorigenic, pro-angiogenic, and immunosuppressive factors such as IL10, TGFβ, and VEGFA; whereas M1 macrophages produce pro-inflammatory cytokines such as TNFα, IL1, IL12, and IFNγ, and reactive oxygen species, which prevent tumor growth." (PMID 34517894, 2021). "However, PD-L1 expression is not necessarily a sign of immune evasion but can also reflect an active endogenous anti-tumour immune response resulting from production of pro-inflammatory IFNγ in the TME." (PMID 34642463, 2021). "Moreover, tumor apoptosis increased infiltration of CD 8 cells along with an increase in interferon-gamma (IFN-γ), and IL-2 levels were only observed in PSMA-expressing cells." (PMID 33440664, 2021). "Moreover, the capacity of anti-PD1 to elicit interferon-gamma production by tumor-infiltrating T cells was reduced upon social stress." (PMID 34947849, 2021).
tumor (continued). "Furthermore, we applied SFV/IFNg alone or in combination with Pam3 for in vivo therapy of 4T1 tumor-bearing mice to evaluate tumor growth inhibition." (PMID 34835178, 2021). "Additionally, strong correlation of IFNγ-induced signatures with NAMPT expression in multiple tumors suggests that this pathway of potential tumor control occurs more generally." (PMID 33976173, 2021). "Interestingly, in patient 8 the most expanded circulating MAMI-reactive IFNγ+Teff clone also dominated the tumor-infiltrating Tconv population, indicating a dynamic exchange between the two compartments during a MAMI-specific immune response." (PMID 33602930, 2021). "Vaccination with the 7 selected peptide combination was screened to see if it could provide tumour therapy in the B16 tumour model constitutively expressing HLA-DP4 (B16cDP4) or expressing DP4 under an IFNγ inducible promoter (B16iDP4)." (PMID 34858415, 2021). "Numerous cytokines, including tumor necrosis factor-alpha, interleukin-1, interleukin-6, and interferon-gamma, released either by tumor cells or by the host as inflammatory reaction to tumor cells, have been postulated to play a role in the etiology of cancer cachexia." (PMID 34055649, 2021). "However, the remarkable exception to this tumor-associated suppression was the MAC-MT subset, which showed a significant increase in the expression in IFNγ-, TNF-, and fatty acid–stimulated macrophage gene signatures." (PMID 34936871, 2021). "Indeed, the anti-HER2 mAb trastuzumab can increase IFNγ production through the MyD88 pathway, and IFNγ induces PD-L1 expression on tumor cells." (PMID 34572847, 2021). "All vaccinated mice showed OVA-specific CD8+ T cells, evaluated by IFNγ ELISpot assay, starting from 8 days after immunization, corresponding to 14 days after tumor injection (837 ± 167 spot forming cells (SFC)/106 cells, mean ± SD) reaching a peak at 35 days (1064 ± 293 SFC/106 cells)." (PMID 33672349, 2021). "Utilizing Arid1a-mutated OCCC mice treated with the HDAC6 inhibitor and anti-PD-L1 immune checkpoint blockade, they further found that tumor burden reduced and mice survival improved because of the activation and increased presence of interferon-gamma-positive CD8 T cells." (PMID 34671561, 2021). "Given the paramount role of IFNG in orchestrating the anti-tumor immune response, a comprehensive understanding of the role of IFNG in GBM may help to optimize the current treatment of this disease." (PMID 34566988, 2021). "Interestingly, TAM derived IFNγ has been shown to induce PD-L1 expression in lung cancer and by this mechanism supported tumor progression; and (iii) CTL exclusion from intra-tumoral environment." (PMID 34988021, 2021). "The recruitment and polarization of M1 TAMs may be promoted by the secretion of a variety of molecular factors, for example, the pro-inflammatory cytokine IFNγ, by tumor cells and, interestingly, by activated fibroblasts (like pro-inflammatory CAFs)." (PMID 34183054, 2021). "Previous studies have validated that IFNG could suppress SLC7A11, causing reduced cystine uptake, enhanced tumor lipid oxidation and ferroptosis, and improved tumor control." (PMID 34885178, 2021). "The secretion of interferon gamma (IFNγ) and the enhancement of tumor PD-L1 expression promote each other, resulting in CD8+ and CD3+ T cells enrichment around NPC tissues, and the accumulation of these immune cells promotes the immune response to tumor tissue 30, 33-34." (PMID 34539884, 2021). "Interestingly, the anti-tumor cytokine IFNγ-expression by T cells was significantly enhanced through the combination of anti-PD-1 antibody with Lm-ANXA2 vaccine therapy." (PMID 34638560, 2021). "IFNG signaling is a well-established pathway in tumor control." (PMID 34147519, 2021).